TNF (tumor necrosis factor)
Diseases named in the same sentence as TNF in open-access papers (continued):
Sharing a sentence is not in itself a finding about the gene and the disease.
tumor (continued). "Moreover, functional assays to evaluate the ability of T cells to produce key effector cytokines, such as IFN-γ and TNF-α, would provide a more comprehensive understanding of their capacity to mediate effective anti-tumor immunity within the TME." (PMID 40475779, 2025). "In response to injury, inflammation, or neoplasia and infection, inflammatory monocytes mature into inflammatory macrophages, which participate in an inflammatory response by secreting chemokines and tumor necrosis factor-alpha (TNF-α)." (PMID 40161128, 2025). "The rationale is supported by our data and the broader understanding that TNF-α fosters a pro-tumor microenvironment; neutralizing it might impair the tumor’s support network." (PMID 40299527, 2025). "Finally, GFRAL knockdown in tumor cells inhibited GDF15-induced TNF-α and EGF expression, confirming GFRAL as the mediator of GDF15 downstream signaling." (PMID 41035818, 2025). "However, inflammation-induced disruption of the BBB - mediated by TANs and cytokines (e.g. IL-1β, TNF-α, and IL-6) - can increase vascular permeability and create a permissive environment for tumor cell infiltration into the CNS." (PMID 40496607, 2025). "At this time, immune dysregulation may occur, leading to a cytokine storm The massive release of cytokines such as IFN-γ, TNF-α, and IL-6 not only attacks tumor cells but also indirectly damages skeletal muscle cells." (PMID 40242775, 2025). "Moreover, AHR-high expression was associated with inflammatory response, IL-2 and IL-6 signalling, and tumour necrosis factor alpha (TNF-α) signalling via NF-κB in both ER+ and ER- tumours." (PMID 40646277, 2025). "As a tumor-targeting system, non-pathogenic E. coli strain MG1655 can deliver TNF-α specifically in tumor sites, thereby localizing its tumor-killing effect and achieving precise control over the targeted therapy." (PMID 39921821, 2025). "Both IFN-γ and TNF-α release were upregulated in tumor mice receiving sNK cells." (PMID 40805135, 2025). "At the same time, MAIT cells secrete cytokines such as IFN‐γ and TNF‐α to activate DCs, enhance adaptive immune responses, and synergize with NK cells to inhibit tumor progression; on the other hand, immunosuppressive factors in the TME can induce functional exhaustion of MAIT cells." (PMID 41179703, 2025). "Tumor-secreted inflammation occurs due to the secretion of various inflammatory signal molecules by macrophages, such as interleukin-6 (IL-6), interleukin-1 (IL-1), and tumor necrosis factor-α (TNF-α)." (PMID 40865948, 2025). "In addition, we showed that RA significantly attenuates TNF-α-induced NF-κB activation in a reporter assay, indicating its ability to modulate inflammatory signaling pathways commonly involved in tumor progression." (PMID 40650205, 2025). "Due to their major role in the tumor cell progression, the levels of the pro-inflammatory cytokines TNF-α and IL-6 were evaluated in dynamics during Nivolumab treatment in three selected serum samples (T1–T3, timepoints of Nivolumab treatment) from each patient at 3-month intervals." (PMID 40564098, 2025). "Additionally, SYD exerts control over the IL‐17/TNF/NF‐κB signaling pathway, leading to the prevention of tumor cell differentiation, reduced cell proliferation, and alleviated mouse intestinal inflammation." (PMID 40119640, 2025). "Modified MUC1 protein-functionalized AuNPs were found to be potent macrophage activators, promoting the release of IL-6, IL-10, IL-12, and TNF-α from peritoneal macrophages and driving predominant M1 polarization, highlighting their potential as a potent tumor vaccine." (PMID 40801739, 2025). "Notably, TNF-α exhibits cytotoxic effects on tumor cells and also stimulates the secretion of IL-1β and IL-6." (PMID 40559782, 2025). "TNF was initially identified and named for its anti-tumor properties." (PMID 41333471, 2025).
tumor (continued). "Furthermore, it produced greater tumor growth inhibition and a ∼50% stronger reduction in NF-κB expression (≈3-fold vs. ≈2-fold decrease) by inhibiting the TNFα-induced NF-κB complex." (PMID 41443414, 2025). "Additionally, ELISA results showed elevated levels of RFA‐induced anti‐tumor cytokines, including tumor necrosis factor‐α (TNF‐α), interleukin‐2 (IL‐2), interleukin‐12 (IL‐12), and interferon‐γ (IFN‐γ)." (PMID 40956367, 2025). "Pro-inflammatory cytokines within the tumor microenvironment, such as IL-6 and TNF-α, may stimulate MUC16 transcription via JAK/STAT and NF-κB signaling pathways." (PMID 40422614, 2025). "However, under specific molecular conditions, such as inhibition of anti-apoptotic proteins or S-nitrosylation of key survival regulators, TNF-α can induce apoptosis and suppress tumor traits." (PMID 40558596, 2025). "At the same time, the immunohistochemical staining of tumor slices demonstrated that HIFU could upregulate the expressions of TNF-α and IFN-γ in tumors and those of the NP-PF + H group were the highest among all the groups." (PMID 40698150, 2025). "Cisplatin-triggered ferroptotic tumor cells reprogram TANs toward an N1-like phenotype, characterized by the upregulation of cytotoxic effectors such as TNF-α, granzyme B, and NE, as well as chemokines and cytokines including CCL2, CCL3, CXCL9, CXCL10, CXCL11, IL-12A, and IL-12B." (PMID 40805288, 2025). "Additionally, γδ T cells usually produce higher amounts of anti-tumor cytokines (such as TNF and IFN-γ) than pro-tumor cytokines (for instance: IL-4, IL-10, IL-17, IL-22, and IL-35) within the TME, reflecting their prognostic value in cancer patients." (PMID 40148988, 2025). "TNF-α, IL-1β, and iNOS are inflammatory cytokines that are secreted by M1 macrophages and can eliminate infectious organisms such as bacteria, viruses, and malignant tumor cells, then macrophages phagocytose cells that are dead." (PMID 39775258, 2025). "Notably, the TIM-3+ PD-1+ dual positive tumor-infiltrating T lymphocytes (TILs) are defined by their failure to proliferate with reduced expression of IL-2, TNF-α, and IFN-γ and these cells exhibit the most pronounced exhausted state." (PMID 40872312, 2025). "Additionally, we observed a notable elevation of the secretion of key inflammatory cytokines and effector molecules within the tumor, including TNF‐α, Granzyme B, and IFN‐γ, suggesting the activation of anti‐tumor responses." (PMID 39761175, 2025). "Furthermore, NK derived exosomes loaded with miR-30c, upregulated IFN-γ and TNF-α secretion and bolstered the cytotoxicity of NK cells to lung cancer cells, thus stopping tumor growth in vivo." (PMID 39961904, 2025). "Additionally, FIRRE has been shown to regulate the expression of immunomodulatory genes, such as VCAM1 and TNF-α, indicating its role in modulating the tumor immune microenvironment." (PMID 39981249, 2025). "In addition, SDA and its metabolites can inhibit nuclear factor kappa B (NF-kB), which reduces the expression of inflammatory cytokines (such as IL-6 and TNF-α) that contribute to tumor development." (PMID 40507897, 2025). "Collectively, these findings suggest that immune cells may selectively recognize tumour cells through fine‐tuned modulation of TNF signalling dynamics and receptor–ligand interactions." (PMID 40770837, 2025). "Innate immune cells, such as mature dendritic cells (mDCs) and M1-like tumor-associated macrophages (TAMs), secrete cytokines, such as IFN-α, IL-12, IL-18, and TNF, along with chemokines like CXCL9, CXCL10, and CCL21, which effectively suppress tumor angiogenesis." (PMID 40322886, 2025). "Altogether, our results suggest that IFNγ is critical for promoting the growth and the expression of CXCL5 of 3D tumor cells and that TNFα may be a downstream effector molecule of LPS-stimulation." (PMID 40050422, 2025).
tumor (continued). "Correlation analysis of secreted factor levels, hearing parameters, and tumor size in the TNF-α High and Low groups revealed associations not apparent prior to grouping." (PMID 39923035, 2025). "This hypothesis was further confirmed by the upregulation of the surface expression of CD107a and by the release of TNFα by MCs incubated with tumoral organoids, an effect dependent on IL-33 released by tumor organoids." (PMID 41368640, 2025). "SE modulated IL-2, IL-4, IL-6, IL-17, IFN-γ, and TNF-α in tumor environment." (PMID 40807278, 2025). "Elevated levels of pro-inflammatory cytokines such as interleukin-6 (IL-6) and tumor necrosis factor-alpha (TNF-α) promote survival pathways, chemoresistance, and immune evasion, while anti-inflammatory cytokines like IL-10 further suppress effective anti-tumor immunity." (PMID 40486628, 2025). "This chronic inflammatory state promotes the release of cytokines (e.g., IL-1β, IL-6, IL-10, IL-18, TNF-α) and growth factors that facilitate tumor cell proliferation, invasion, and angiogenesis, while simultaneously impairing effective immune surveillance against malignant cells." (PMID 41114747, 2025). "Moreover, the significant increase in effector/memory and cytotoxic T-cell populations, including those producing IFNγ and TNFα, also highlights a shift towards a more active immune response capable of targeting and destroying tumor cells." (PMID 40750787, 2025). "Additionally, NADPH oxidase 5 (NOX5) is overexpressed in ESCC, activating intratumoral Src/NF-κB signaling, which stimulates tumor cells to secrete tumor necrosis factor-alpha (TNF-α), IL-1β, and lactate." (PMID 40134607, 2025). "In cancer patients, the tumor microenvironment triggers a persistent systemic inflammatory response characterized by elevated cytokines such as IL-6, TNF-α, and IL-1β, which can impair renal vascular tone and lead to renal hypoperfusion and structural kidney damage over time." (PMID 40722492, 2025). "In aging, TNF-α promotes tissue damage and neuroinflammation, while in cancer, it activates NF-κB signaling, enhancing angiogenesis and metastasis, ultimately creating a microenvironment that supports tumor survival." (PMID 41294748, 2025). "The APU-R848-IONP platform reprogrammed tumor-associated macrophages by coupling R848-driven and IONP-mediated regulation, reducing the M2/M1 macrophage ratio by 51% and elevating tumoricidal cytokines (TNF-α, IL-12)." (PMID 40648713, 2025). "Our previous results have demonstrated that CAMP attachment to NE significantly increases the release of myeloperoxidase (MPO) and tumor necrosis factor (TNF)‐α compared with untreated NEs showing activation and a shift towards anti‐tumor N1 phenotype in vitro." (PMID 39801750, 2025). "In turn, the cytokines produced by activated macrophages could further activate NF-κB and increase the expression of various inflammatory and tumor-promoting cytokines (such as IL-6, IL-1α, and TNF-α) and genes such as BCL-2 and BCL-XL." (PMID 40109347, 2025). "Moreover, ELISA analysis detected a substantial increase in both IFN-γ and TNF-α secretion in the supernatant when CD8+ OT-I T cells were cocultured with Usp22 KO or pharmacological inhibition tumor cells." (PMID 41252204, 2025). "In addition, the DCs supplied with the supernatant from OVV-mNbTIM3-infected tumor cells produced much higher concentrations of IL-12, TNF-α, and IL-1β." (PMID 41291902, 2025). "Chronic inflammation may drive thyroid cell proliferation and tumor formation through pro-inflammatory cytokines (e.g., TNF-α, IL-6) and vascular endothelial growth factor (VEGF)." (PMID 41409611, 2025). "Notably, pro-tumor pathways including TNF, EGF, VEGF, FGF, and WNT are enriched in the NT5E-positive group." (PMID 41487509, 2025).
tumor (continued). "Our cytokine analysis revealed decreased levels of IFN-γ and TNF-α in the combination treatment group at this tumor suppression time point, suggesting the establishment of a sustainable antitumor immune environment rather than an acute, potentially harmful inflammatory state." (PMID 40347254, 2025). "Finally, we assessed cytokine production at the protein level by immunofluorescent staining of frozen tumor sections for IL1β, IFNβ, and TNFα." (PMID 41401057, 2025). "The TNF-α signaling pathway plays an important role in tumor progression." (PMID 41216196, 2025). "Noteworthily, Prohep elevated Helicobacter typhlonius inversely correlated to tumor count < 2 mm (p < 0.05), and pro-inflammatory cytokines TNF-α (p < 0.05), while being positively correlated to the abundance of fecal butyrate, propionate and acetate (p < 0.05)." (PMID 39641861, 2025). "Various immune-activating cytokines and chemokines (i.e. CXCL11, CCL2/5/19, FLTL3, IFN-α/β/γ, IL2/7/12/15/18/23/24, TNF-α, etc.)are being investigated on preclinical tumor models (neuroblastoma, breast tumor, lymphoma, lung cancer, glioma, melanoma, etc.)and in clinical trials." (PMID 40697381, 2025). "IL-2 and TNF-α expression presented a significant correlation with tumor stage." (PMID 40869161, 2025). "Furthermore, in Ova-IC–stimulated tumours, we observed increased intracellular TNFα in Ly6C+MHC-II+ mdTAMs that had bound or internalised Ova-IC compared to Ova-647-stimulated cells, but this increase was not present in Ly6C+MHC-II– mdTAMs." (PMID 40523200, 2025). "Th1 T cells are the primary source of the inflammatory cytokines interferon (IFN)-ꝩ, interleukin (IL)-2, and tumor necrosis factor (TNF), which induce maturation of APCs, more effective presentation of tumor antigens, and maturation of CD8+ cells to fully functional CTLs." (PMID 40940764, 2025). "More elusive is the source of TNF driving Treg expansion in the tumor microenvironment." (PMID 40977146, 2025). "However, the same immunogenic signals from tumors can also facilitate tumor progression by reorganizing the stroma and promoting angiogenesis, highlighting the inherent dual nature of TNF-α-mediated necroptosis." (PMID 41584509, 2025). "When M1 MEVs are introduced into the tumor microenvironment, they influence the surrounding M2 macrophages to adopt a more pro-inflammatory, tumor-fighting state by increasing the secretion of cytokines such as TNF-α and upregulating pro-inflammatory markers like CXCL8." (PMID 40330466, 2025). "TNF-α, produced by ILC1s, plays a significant role in tumor suppression." (PMID 40497988, 2025). "Flow cytometry analysis on re-stimulated splenocytes, showed that mice treated with CBL0137 had significantly higher numbers of tumor-specific T cells, as shown by the higher percentages of T cells expressing IL-2, IFNγ or TNFα, particularly in the CD4+ T cell compartment." (PMID 39706891, 2025). "TGF-β1 and TNF-α have regulatory roles during tumor progression." (PMID 40833805, 2025). "Notably, NF-κB can be activated independently of TLRs by inflammatory cytokines, such as Tumor Necrosis Factor-alpha (TNF-α), which are abundant in the tumor microenvironment." (PMID 40821794, 2025). "We also demonstrate the role of IFN-γ and TNF-α in inducing tumor differentiation." (PMID 39851518, 2025). "TNFα promotes the death of tumor cells by inducing programmed necrosis." (PMID 41573646, 2025). "Furthermore, LCRC frequently signals through fibroblast-secreted collagen that binds tumor cell α1β1 integrins, as well as through macrophage-secreted TNF that interacts with tumor cell TNF receptors." (PMID 41450739, 2025). "TNF plays multiple roles in cancer, including some that are opposing, due to the complex interactions among the cells that produce and respond to this cytokine within the tumor microenvironment." (PMID 40977146, 2025).
tumor (continued). "Additionally, in cases with a poor prognosis, HIF1A-driven pathways, such as PI3K/AKT, TNF-α, and Wnt, promote tumour proliferation and survival by metabolic reprogramming, as well as upregulation of metastasis-promoting genes such as MMP1, TWIST2, and ITGB1." (PMID 41007296, 2025). "Initially, they may infiltrate the tumor due to passive entrapment within its disorganized vasculature, followed by further penetration driven by inflammation triggered by a sudden increase in TNFα levels in the tumor vessels." (PMID 40430828, 2025). "In addition to inhibiting key components of the NF‐κB pathway, targeting TNF‐α, which acts as an activator and effector of the NF‐κB pathway, is also expected to achieve the goal of suppressing tumor growth." (PMID 40859961, 2025). "However, more recent studies have uncovered a paradoxical role in the tumor microenvironment, where TNF can also act as an immunosuppressive cytokine." (PMID 41568361, 2025). "Conversely, M1 macrophages exhibit anti-tumor properties by producing pro-inflammatory cytokines [e.g., IL-12, tumor necrosis factor-alpha (TNF-α)], releasing cytotoxic agents like reactive oxygen species (ROS) and nitric oxide (NO), and presenting tumor antigens to activate T cells." (PMID 40230883, 2025). "Furthermore, P. gingivalis recruits myeloid cells, alters the tumor microenvironment, and increases the production of pro-inflammatory cytokines, such as TNF-α, IL-6, and IL-1β, thereby further driving tumor growth." (PMID 41473772, 2025). "However, studies suggest that reduced IL-10 expression permits increased angiogenesis and heightened activity of VEGF, IL-1β, TNF-α, IL-6, and NF-κB, ultimately enhancing tumor growth." (PMID 40100373, 2025). "For example, tumor necrosis factor (TNF) blockade may enhance ICI efficacy by supporting tumor-infiltrating lymphocyte survival, while IL-6 receptor blockade could induce remission without impairing anti-tumor immunity." (PMID 40292281, 2025). "IFN-γ induces tumor vascular regression, while TNF-α bursts them." (PMID 40370455, 2025). "M1, induced by interferon-gamma (IFN-γ) and lipopolysaccharide (LPS), express high levels of inducible nitric oxide synthase (iNOS), interleukin (IL)-12, and tumor necrosis factor-alpha (TNF-α), promoting anti-tumor immunity through direct cytotoxicity and T cell activation." (PMID 40806379, 2025). "To assess the PCa tumour microenvironment for impaired immunity, we also performed a pilot RNA-expression analysis for PCa-associated immunological factors (IL1β, IL10, IL18, TNF-α, TLR4, GATA3, CD68)." (PMID 40430084, 2025). "Indeed, it has been reported that TNFα renders tumour vessels more permeable, facilitating the delivery of anticancer drug agents to solid tumours." (PMID 41188521, 2025). "Research has found that under normal circumstances, low levels of TNF-α in plasma have physiological functions such as killing or inhibiting tumor cells, enhancing the phagocytic ability of neutrophils, resisting infections, and promoting cell proliferation and differentiation." (PMID 40430440, 2025). "In addition, TNF-α can stimulate the production of IL-6 and IL-8, and IL-6 can be self-induced in tumor cells, which in turn promotes the growth of tumor cells." (PMID 41154714, 2025). "Notably, MC function is dynamically regulated by tumor micro-environmental signals: IL-1, IL-4, IL-6, and TNF-α activate antitumor effects, whereas VEGF, matrix metalloproteinase, trypsin-like enzymes, and IL-10 promote malignant progression." (PMID 40960294, 2025). "M1, present in early tumor development, promotes inflammation and is capable of releasing TNFα, which is speculated to contribute to cachexia." (PMID 40427098, 2025). "The introduction of a tumor that secretes TNF results in notable muscle wasting in mice, and administration of TNF or IL-1 in living organisms leads to an increase in nitrogen excretion from skeletal muscle and a decline in body protein levels in otherwise unaffected animals." (PMID 39838305, 2025).